CD80 (CD80 molecule)
Diseases named in the same sentence as CD80 in open-access papers (continued):
Sharing a sentence is not in itself a finding about the gene and the disease.
tumor (continued). "used a murine model combining the implantation of wild-type, CD274KO, or CD80KO tumor cells, in wild-type, CD274KO, or CD80KO mice, to modulate the PD-L1/CD80 interaction in cis and trans." (PMID 41425548, 2025). "We then investigated the anti-tumor immune responses by evaluating the expression levels of CD3+, CD4+, and CD8+ T cells, as well as DC maturation (CD11c+, CD86, and CD80) in tumors." (PMID 40234392, 2025). "Splenic CD80+/CD86+ DC populations increased markedly, correlating with expanded tumor-infiltrating CD8+ T cells." (PMID 40892295, 2025). "The co-stimulatory molecules CD80 and CD86 were abundantly expressed on activated dendritic cells, whereas I-A/IE, an MHC-II molecule, was detected on DCs loaded with tumor antigens." (PMID 40386771, 2025). "Using these models, we demonstrate that radiation results in significant upregulation of the costimulatory molecules CD80 and CD86 on monocytes and macrophages in the tumor, and on monocytes that are recruited to the tumor following radiation." (PMID 41417245, 2025). "A comprehensive analysis of ICPs revealed significantly higher levels of ICPs such as CD44, CD80, CD86, and CTLA-4 in the high-TKT expression group, thereby allowing tumor cells to evade immune surveillance, and facilitating tumor progression." (PMID 40230848, 2025). "ACY241 increases the expression of B7 (CD80, CD86) and MHC (class I, class II) in tumor and dendritic cells." (PMID 40260239, 2025). "These tumour samples were precisely sliced and subsequently stained using DAPI, as well as antibodies against CD11b, CD206, and CD80." (PMID 41020311, 2025). "Candidates possibly involved in modulating T cell activity include CD28/CD80, ICOS/ICOSL, OX-40/OX-40L, and B7-H6/NKp30, but very little is known as to their role in tumor–immune communication." (PMID 40649953, 2025). "For the immune part, we focused on the TCR-mediated signaling pathway and major immune checkpoints including PD-1, PD-L1, CD28, CD80/CD86, LAG3, CTLA4, TIGIT, CD155, OX40, OX40L, 4-1BB, and 4-1BBL (expressed on T cells, tumor cells, or APCs)." (PMID 40276607, 2025). "As expected, the group receiving aPD-1@NP displayed a slightly increased proportion of M1 TAMs (CD80 as marker) and CD8+ T cells and a mildly reduced proportion of M2 TAMs (CD206 as marker), Tregs and MDSCs in the tumor tissues." (PMID 40380202, 2025). "As the most potent APCs in the body, DCs upregulate the expression of costimulatory molecules such as CD80, CD86, CD40, and the chemokine receptor CCR7 upon stimulation with tumor antigens." (PMID 40040692, 2025). "After migrating to a tumor, they differentiate from SCL to an effector state, which requires costimulation by CD80 and CD86 of APC in the TME." (PMID 39835538, 2025). "This process subsequently activated CD80+ CD86+ macrophages, thereby enhancing the presentation of tumor antigens." (PMID 41583493, 2025). "The secretion of exosomal peptide MHC I is transferred to CD8+ T cells under the influence of released IL-2 and exosomal CD80, leading to increased proliferation of CD8+ T cells and the production of a more robust anti-tumor immune response in vivo." (PMID 40141358, 2025). "CD80 and CD206, two typical markers of antitumor/pro‐tumor (AT/PT) macrophages, were widely utilized." (PMID 40344649, 2025). "CTLA-4 competes with the costimulatory receptor CD28 for binding B7 molecules (CD80/86) on antigen-presenting cells, while PD-1 inhibits TCR signaling upon engagement with PD-L1 on tumor or immune cells." (PMID 40725830, 2025). "B7 family proteins (CD80 and CD86) on antigen-presenting cells (APCs) bind to CD28 on T cells, activating them to target tumor cells." (PMID 40012016, 2025). "In particular, the data indicate a stronger immunosuppressive role of CD80 compared to CD86 in a tumor tissue context, suggesting the exploration of anti-CTLA-4 and anti-CD80 antibody combinations in animal models." (PMID 40725864, 2025).
tumor (continued). "Further evaluation of the immune effects of ChS-Ce6-induced pyroptosis showed a significant increase in the proportion of CD80+CD86+ cells in tumor-draining lymph nodes and a markedly higher infiltration of CD4+ and CD8+ T cells in the tumor tissues." (PMID 40698137, 2025). "This was associated with a reduction in Treg proportions in the tumor, and the authors similarly conclude that costimulation by CD80 and CD86 is more important for Treg than for the other T cells involved in tumor control." (PMID 41417245, 2025). "Previous studies consistently reported that the expressions of LAG-3, PD-1, PD-L1, CD28, CD80, CD27 and CTLA-4 were relevant to the immunosuppression in the tumor microenvironment." (PMID 39781354, 2025). "Preclinical studies demonstrate that sPD-1 delivery via gene transfer or systemic administration disrupts PD-L1-mediated T-cell inhibition, including blocking interactions with B7-1 (CD80), which enhances anti-tumor immunity." (PMID 40283180, 2025). "In the tumor-draining lymph nodes (tdLNs), SAN-TLRa vaccination slightly increased the proportion of CD80+ and CD86+ DCs, while SAN-TLRa vaccination followed by BMAA treatment further enhanced the DC maturation." (PMID 40083927, 2025). "TAMs contribute to T-cell dysfunction by expressing immunosuppressive molecules, such as CD80, CD86, and VISTA, which inhibit T-cell activation and impair the anti-tumor immunity." (PMID 40722951, 2025). "ICI prevent interaction of receptor and corresponding ligands such as CTLA-4/CD80/86, PD-1/PD-L1/2, PD-L1/2/CD80, and LAG-3/MHC-II, and thus override tumor’s survival mechanisms, especially the inhibition of T cell activity." (PMID 39762846, 2025). "TCMs co-cultured with B16-F10 tumor cells at a 1:10 ratio increased their relative expression of MHC1, MHC2, CD80, and CD86 over the course of 48 h as compared to TCMs cultured in medium alone." (PMID 41050935, 2025). "This upregulation of CD80 and CD86 on macrophages suppresses anti-tumor immunity following radiation therapy, despite the known importance of CD80 and CD86 in conventional costimulation." (PMID 41417245, 2025). "In this study, we evaluated the levels of CD80 and CD86 in tumor tissues and observed an upregulation in the miR-497-NBs+US and miR-497/SK-NBs+US treatment groups." (PMID 41583493, 2025). "This includes PD-L1:PD-1 and CD80/86:CTLA-4, which act to block inhibitory signaling between tumor cells and T cells and antigen-presenting cells (APCs) and T cells, respectively." (PMID 41322194, 2025). "Immune profiling showed CWP + X-ray + aPD-L1 treatment enhanced mature DCs (CD80+CD86+) by 24.5% and tumor-infiltrating CD8+ T cells by 4.8% versus controls, confirming enhanced antitumor immunity through ICD potentiation." (PMID 40892295, 2025). "To distinguish the subtypes of increased macrophages observed in the tumor-infiltrating lymphocytes analysis, we used MCP-1, CD80, and iNOS as M1 markers, while CD206 as an M2 marker." (PMID 40836337, 2025). "Treg cells can restrict the activity of antigen-presenting cells by downregulating the expression of CD80 and CD86 in a CTLA4-dependent way, therefore preventing the presentation of tumor antigens and the activation of tumor-specific T cells." (PMID 41019045, 2025). "Intratumoral delivery of rM-FC effectively recruits and activates dendritic cells (DCs), especially CD103+ DCs and CD80+CD86+ DCs, further inducing sufficient migration of effector memory T cells into the tumor microenvironment." (PMID 39780958, 2025). "A significantly elevated expression of checkpoint inhibitors was detected in Cluster two tumours, including PD-1, PD-L1, CTLA4, CD80/CD86 costimulatory molecules, and emerging targets like TIGIT and LAG3." (PMID 41050056, 2025).
tumor (continued). "In contrast, HMDMs co-cultured with untreated A375s are associated with expression of CD40, CD80, and CD206, meaning that these macrophages have adopted a complex tumor-associated macrophage state and, if given the appropriate cues, may be manipulated into an anti-tumor state." (PMID 40539073, 2025). "IgE engagement of monocytes via the Fc region induced tumor cell cytotoxicity and a pro-inflammatory shift with upregulation of immune-stimulatory CD40, CD80 and CD86, and downregulation of scavenger CD163, cell surface molecules." (PMID 40074330, 2025). "After that, the tumor tissue microarrays were subjected to multi-label immunofluorescence staining of CD28 (yellow), CD68 (green), CD80 (red), and CD8 (orange)." (PMID 40541951, 2025). "This enables the tumor to evade immune detection by inhibiting inflammatory cytokines like TNF-α and suppressing MHC II, CD80, and CD86 expression." (PMID 39118076, 2024). "Transforming growth factor-β (TGF-β) secreted by CAFs limits T cell infiltration into the tumor while also downregulating the expression of MHC-II, CD80, and CD40 on the surface of dendritic cells in the TME, suppressing anti-tumor immunity." (PMID 38605943, 2024). "Cytotoxic T lymphocyte associated protein 4 (CTLA4) is an immune-checkpoint molecule on T cells which interactes with CD80 (B7-1) and CD86 (B7-2) on tumor cells to inhibit the induction phase of the T cell response." (PMID 38439112, 2024). "CTLA4, a T-cell co-stimulatory molecule, primarily functions by binding with co-stimulatory molecules CD80/CD86, thereby inhibiting T-cell activity and weakening immune response, ultimately promoting tumor growth and metastasis." (PMID 38227081, 2024). "Overall expression of CD80 in CCH was similar to that in HS (73.3 ± 37.4% vs 62.1 ± 46.4%), while significantly more CD86 expressing tumor cells were found in CCH (94.7 ± 10.3%) when compared to HS (57.6 ± 11.0%)." (PMID 39619201, 2024). "The MART1-specific CTL generated by aAPCs, transduced with CD80, CD83 and HLA-A * 0201 can persist in vivo and induce anti-tumour response." (PMID 39215816, 2024). "butyrate restrains anti-CTLA-4-induced up-regulation of CD80/CD86 on dendritic cells and ICOS on T cells, accumulation of tumor-specific T cells and memory T cells." (PMID 39351241, 2024). "Compared to splenic myeloid cells, we observed remarkable co-expression of I-A/I-E, CD80, and CD86 with Dectin-1 in tumoral myeloid cells in both tumour models." (PMID 38668817, 2024). "Our results showed the highest percentage of mature DCs in the combination treatment group along with increased CD86, CD80, and MHC-II in tumor-infiltrating DCs compared with the control." (PMID 39772073, 2024). "Our findings highlight the precise binding specificity of AYA22T-R2-13 for CTLA4-B7-1/B7-2 (CD80/CD86) or CD94/NKG2A-HLA-E interactions, positioning it as a valuable tool for immune checkpoint blockade aptamer research in murine tumor models." (PMID 38473398, 2024). "Tremelimumab is another humanized IgG2 monoclonal antibody against CTLA-4, which binds to CTLA-4 and blocks its interaction with ligands CD80 and CD86, thereby enhancing T cell response to tumor cells." (PMID 38177102, 2024). "In contrast to larger variations in CD80 expression, mean percentages of CD86 expressing tumor cells among biological replicates were remarkably close to each other in HS between 51.7% and 62.7%." (PMID 39619201, 2024). "Consistent with the in vitro results, the proportion of mature DCs (CD11C+CD40+, CD80+, or CD86+) in tumor tissues and tumor-draining lymph nodes (TDLNs) was highly upregulated compared to that in the control group." (PMID 38994018, 2024). "Current research suggests that CD80 is a potential therapeutic target for improving the prognosis of patients with LUAD and enhancing the effectiveness of biologically targeted anti-tumor treatments." (PMID 39139574, 2024).
tumor (continued). "The increased interaction among CD80, PD-L1, and CTLA-4 presents a new concept for anti-tumor immunotherapy." (PMID 39575257, 2024). "The surface expression of activation markers, including CD80, CD86, and MHC-I on tumor-infiltrating DCs, was markedly increased in TMPyP4-treated MC38 tumors." (PMID 39528472, 2024). "Mature DCs highly express MHC I and MHC II, CD80, CD86, and pro-inflammatory factors, activating the anti-tumor immunity." (PMID 39364399, 2024). "CD80 is shown to engage with the T cell inhibitory molecule CTLA4, leading to immune suppression and the promotion of tumor growth." (PMID 38891044, 2024). "Specifically, CD80 and CD86 were higher in tumour-residing CCR7+ DCs, confirmed at a protein level, while Icosl was significantly higher in migrated CCR7+ DCs in the dLN." (PMID 38267413, 2024). "Meanwhile, the enhanced CD80+ macrophages after tumor cell supernatant re‐stimulation implied that the systemic circulating monocytes/macrophages in the BG/OVA@EcN‐treated group might more likely differentiate into pro‐inflammatory macrophages after infiltration into the tumor tissues." (PMID 38009498, 2024). "Compared to naïve DCs, DCs challenged with tumor supernatant exhibited significantly suppressed expression of MHC II, CD40, CD80, and CD86." (PMID 38164187, 2024). "The CD80 fusion protein, bi/tri-specific antibody, CAR-T, etc. all play a role in the development of tumor immunotherapy." (PMID 39575257, 2024). "Studies from other laboratories have shown that CD80 expression on TISCs in the context of CTLA4 on immune cells results in a blunted effector anti-tumor response and promotes tumor progression." (PMID 38891044, 2024). "To further explore the impact of aT-sEV PD-1/CD80 on the efficacy of anti-PD-1 immunotherapy, we utilised mice bearing MC38 tumours as an appropriate cancer model due to their ability to elicit a moderate immune response." (PMID 38719909, 2024). "Similar to CD80, CD86 is also a co-stimulatory molecule that enhances T cell activation and proliferation by binding to CD28 on T cells, aiding in the anti-tumor immune response." (PMID 39290697, 2024). "Compared to sham control mice, the CD45hi/CD11bhi compartment significantly expands in tumor-bearing mice and exhibits a myeloid-specific signature composed of VISTA, CD80, PD-L1, CTLA-4, MHCII, CD40, and CD68." (PMID 39123357, 2024). "Mature DCs express co-stimulatory molecules including CD80, CD86, CD40 and CD70, that enables DCs have the capacity to activate T cells and NK cells in tumor immune-surveillance, and directly kill tumor cells." (PMID 38554155, 2024). "Although studies have shown the expression of CD80 and CD86 in tumor cells, the related studies are limited, and their relationship with prognosis is unclear." (PMID 37614091, 2024). "The results showed that CD200, CD80 and TNFRSF14 were the highest in tumor tissues, CD274 (PDL1), CD86, LGALS9, NECTIN2, PDL2, PVR were lower than those in adjacent tissues but higher than those in normal tissues, and FGL1 was the lowest in tumor tissues." (PMID 39120585, 2024). "constructed DC-PC-3 fusion vaccines with specific modifications of CD80 and GM-CSF that strongly promoted T cell proliferation and IFN-γ secretion and induced tumor-specific cytotoxic T lymphocyte responses." (PMID 39575257, 2024). "Initially TNF-γ works by recruiting cohorts (CXCL9, CXCL10, CXCL11, and CXCR3) to promote antigen presentation (MHC class I and class II), T-cell initiation and activation (CD80, CD86, and CD40), and tumor cell killing (Fas and FASL)." (PMID 39835116, 2024). "A moderate correlation was found for mitotic count and CD80 (Spearman’s ρ = 0.49, p < 0.05) as well as mitotic count and CD86 positive tumor cells per mm2 (ρ = 0.34, p < 0.05)." (PMID 38962703, 2024).
tumor (continued). "In an implanted mouse model of metastatic osteosarcoma, treatment with anti-PD-L1 antibody reduced the expression of PD-L1, increased the expression of CD80/CD86 in tumor cells, and increased the expression of CTLA-4 in tumor-infiltrating CD8+ T cells." (PMID 38542199, 2024). "There are only very few studies on cell lines and tumour cells using CTLA-4 receptor ligands, including CD80 and CD86." (PMID 39286684, 2024). "C002-treated tumors exhibited sustained IL-12 production with improved dendritic cells, monocyte-macrophage activity (MHCII, CD80/CD86 upregulation) and a polyfunctional Th1-cell response in the tumor infiltrates." (PMID 38895115, 2024). "Preclinical studies have shown that the allogeneic tumor cell line RCC-26 exhibits natural immunogenic potential, which is enhanced by the expression of CD80 costimulatory molecules and IL-2 secretion." (PMID 39575257, 2024). "Moreover, miR‐210‐3p inhibitor‐treated tumor spheroids notably promote monocyte phenotypic skewing towards M1 polarized macrophages compared to control inhibitor transfected spheroids, as evident from the increased expression of CD80, CD86, iNOS and decreased expression of CD206 and CD163." (PMID 35658112, 2024). "It seems that there is a preferential binding of CTLA-4 to CD80 or CD86, outcompeting CD28 and therefore interrupting T-cell activation, thus mediating immune evasion and escape mechanisms of tumor cells." (PMID 39409094, 2024). "CTLA4 is upregulated in activated regulatory T cells (Tregs) and can bind to CD80 or CD86 on the surface of antigen-presenting cells, thus “shutting down” tumor immunity." (PMID 39091494, 2024). "The results of the study showed the maturity of DCs in tumor draining lymph nodes, the infiltration of CD8+ cytotoxic T lymphocytes and the proportion of CD80+ M1-like TAMs were significantly increased, while CD206+ M2-like TAMs was on the contrary." (PMID 38298192, 2024). "Apoptosis of tumor cells, the ratio of CD8+/CD4+ in CD3+ cells, CD80+CD86 in DD11c+ cells, and IFN-γ+ in CD3+ all were significantly higher than challenge with IL-2 or the microorganism alone." (PMID 38585738, 2024). "We found that CD80 and CCR7 increased on DCs from tumor-infiltrating lymph nodes, suggesting that the α-LNP improves the LNDC maturation and boosts its migration ability." (PMID 39065637, 2024). "The tumor cells from the rapamycin-treated mice expressed higher levels of CD40, CD80, and ICAM-1 than those from the control mice." (PMID 38791040, 2024). "CTLA4 provides a negative modulatory signal to T cells interacting with its primary ligands, CD80 or CD86, on an antigen-presenting cell, and is well described as a key component of tumor immune evasion." (PMID 39478117, 2024). "There are multifactorial potential interactions between T-ALL and stroma that shape the myeloid anti-tumor immune response, including between CD47/SIRPα, PD-L1/PD-1, CD40/CD40L, and CD28/CD80/86." (PMID 36897988, 2023). "We showed an increase in expression for a wide range of co-stimulatory molecules, CD40, CD80, OX40L, and STING on tumor boundary CD11c+ cells." (PMID 38044986, 2023). "XCR1+ cDC1s play a key role in cross-presenting tumor antigens on MHC I to activate antitumoral cytotoxic T cells, and mature LAMP3-high DCs in our dataset had the highest expression of CD80/CD86 costimulatory signals needed to fully activate T cell responses." (PMID 37433281, 2023). "M1 macrophages express CD80, CD86, and HLA-DR surface markers and have anti-tumor effects by producing molecules such as IL-12, reactive oxygen species (ROS), and nitric oxide synthase (iNOS)." (PMID 38066642, 2023). "By binding to B7-1 (CD80) and B7-2 (CD86) ligand on antigen-presenting cells, it regulates the activation of tumor-reactive T cells." (PMID 37834086, 2023). "The logFC of CD80 and IL-6 was 1.433 and 1.233, respectively, suggesting that CD80 and IL-6 were upregulated in HGSOC tumor issues." (PMID 37124547, 2023).